ATP1B2 (ATPase Na+/K+ transporting subunit beta 2)
Description:
This is the non-catalytic component of the active enzyme, which catalyzes the hydrolysis of ATP coupled with the exchange of Na(+) and K(+) ions across the plasma membrane. The exact function of the beta-2 subunit is not known. Mediates cell adhesion of neurons and astrocytes, and promotes neurite outgrowth.
Synonyms: AMOG
Tractability: Small molecule: a drug acting on it is in phase 2 or 3 trials; a high-quality ligand is known; it belongs to a druggable protein family. Antibody: its Gene Ontology location is reachable by antibodies, with high confidence; UniProt places it where antibodies can reach, with medium confidence; UniProt predicts a signal peptide or a membrane-spanning region. PROTAC: ubiquitination databases record sites on it; its protein half-life has been measured.
Safety:
Unwanted effects reported when the protein is acted on. In parentheses: how it was acted on, where the effect was seen, and who reports it.
atrioventricular block (inhibition, acute dosing; renal, cardiovascular; source: Lynch et al. (2017))
cardiac arrhythmia (inhibition, acute dosing; renal, cardiovascular; source: Lynch et al. (2017))
decreased heart rate (inhibition, acute dosing; renal, cardiovascular; source: Lynch et al. (2017))
increased cardiac contractility (inhibition, acute dosing; renal, cardiovascular; source: Lynch et al. (2017))
increased urinary sodium excretion (inhibition, acute dosing; renal, cardiovascular; source: Lynch et al. (2017))
increased urine excretion (inhibition, acute dosing; renal, cardiovascular; source: Lynch et al. (2017))
ventricular fibrillation (inhibition, acute dosing; renal, cardiovascular; source: Lynch et al. (2017))
vomiting (inhibition, acute dosing; renal, cardiovascular; source: Lynch et al. (2017))
Gene: Protein-coding gene on chromosome 17 (7,646,627 to 7,657,770, forward strand). Ensembl gene ENSG00000129244.
Subcellular location: Cell membrane
Pathways (Reactome):
Disease: Potential therapeutics for SARS
Hemostasis: Basigin interactions
Muscle contraction: Ion homeostasis
Transport of small molecules: Ion transport by P-type ATPases
Gene Ontology:
Molecular function: ATPase activator activity; ATPase binding; protein binding; protein-macromolecule adaptor activity; transporter activator activity
Biological process: intracellular potassium ion homeostasis; intracellular sodium ion homeostasis; membrane repolarization; positive regulation of potassium ion import across plasma membrane; positive regulation of sodium ion export across plasma membrane; potassium ion import across plasma membrane; protein stabilization; sodium ion export across plasma membrane; cell communication by electrical coupling involved in cardiac conduction; cell-substrate adhesion; lateral ventricle development; motor behavior; negative regulation of glial cell migration; neuronal-glial interaction involved in hindbrain glial-mediated radial cell migration; photoreceptor cell maintenance; plasma membrane bounded cell projection organization; positive regulation of neuron projection development; retina homeostasis; third ventricle development; transport across blood-brain barrier; potassium ion transport; sodium ion transport
Cellular component: apical plasma membrane; astrocyte projection; lateral plasma membrane; sodium:potassium-exchanging ATPase complex; astrocyte end-foot; cell body membrane; cell periphery; cell projection membrane; external side of plasma membrane; membrane; neuron to neuron synapse; photoreceptor inner segment; plasma membrane; cytoplasm
Genetic constraint (gnomAD): Loss-of-function variants: 12 observed, 36.96 expected, observed/expected ratio (o/e) 0.32, 90% interval 0.21 to 0.53. The upper end of that interval is the gene's LOEUF score, 0.53, which puts it in group 2 of 6, group 1 being the genes least tolerant of losing a copy. Missense variants: 324 observed, 405.8 expected, observed/expected ratio (o/e) 0.8, 90% interval 0.73 to 0.88. Synonymous variants: 139 observed, 147.32 expected, observed/expected ratio (o/e) 0.94, 90% interval 0.82 to 1.09.
Homologues: Orthologues: chimpanzee ATP1B2 (100% identical), macaque ATP1B2 (99% identical), rabbit ATP1B2 (99% identical), pig ATP1B2 (99% identical), dog ATP1B2 (99% identical), rat Atp1b2 (98% identical), mouse Atp1b2 (97% identical), guinea pig ATP1B2 (85% identical), zebrafish atp1b2a (56% identical), tropical clawed frog atp1b2 (56% identical), zebrafish atp1b2b (56% identical). Paralogues in human: ATP1B3 (46% identical), ATP1B1 (40% identical), ATP1B4 (40% identical), ATP4B (39% identical).
Diseases named in the same sentence as ATP1B2 in open-access papers:
ATP1B2 is named in the same sentence as 35 diseases in open-access papers, as found by Europe PMC text mining. Sharing a sentence is not in itself a finding about the gene and the disease. The quoted sentences say what the papers report.
glioma (8 papers, 2017 to 2025). A benign or malignant brain and spinal cord tumor that arises from glial cells (astrocytes, oligodendrocytes, ependymal cells). "Importantly, few of these proteins, namely, ATP1B2, CTNNA3 and MYLK were reported to be downregulated biomarkers in glioma, hepatocellular and breast carcinoma, respectively." (PMID 34728699, 2021).
glioblastoma (7 papers, 2019 to 2025). The most malignant astrocytic tumor (WHO grade IV). "High expression of ATP1B2 has been associated with poor prognosis of patients with glioblastoma, and downregulation of ATP1B2 can inhibit cell growth and induce cell apoptosis and cell-cycle arrest." (PMID 32684846, 2020). "Furthermore, aberrant expression of ATP1B2 has been linked to glioblastoma multiforme (GBM)." (PMID 34060113, 2021). "It was shown that patients with GBM have changes in the isoforms of ATP1B2 and that targeting ATP1B2 induced glioblastoma cells apoptosis." (PMID 34060113, 2021). "In addition, the expression of ATP1B2 in glioblastoma stem-like cells was significantly increased, suggesting its association with the stemness of tumor cells." (PMID 32684846, 2020).
brain tumor (2 papers, 2015 to 2025). "In glioblastoma-derived cells, expression of ATP1B2 down-modulates brain tumor-initiating cell invasion without significantly affecting cell proliferation." (PMID 26191006, 2015).
breast carcinoma (2 papers, 2021 to 2022). "Nucleotide de novo synthesis can increase the stemness and metastasis of breast cancer through cGMP-PKG-MAPK signaling pathway, and DARS-AS1/ATP1B2 regulates the progression of cervical cancer by modulating the cGMP-PKG pathway." (PMID 36106123, 2022).
cerebellar ataxia (2 papers, 2017 to 2021). A neurological syndrome characterized by clumsy and uncoordinated movement of the limbs, trunk, and cranial muscles. "Recently, a structural variation in exon 2 of the ATP1B2 gene has been linked to cerebellar ataxia in Belgian Shepherds." (PMID 34060113, 2021). "ATP1B2 thus represents another candidate gene for human inherited cerebellar ataxias, and SDCA2-affected Malinois puppies may serve as a naturally occurring animal model for this disorder." (PMID 28620085, 2017). "Moreover, our data imply ATP1B2 as an additional candidate gene for human inherited cerebellar ataxias of unknown etiology." (PMID 28620085, 2017).
retinoblastoma (2 papers, 2019 to 2022). A malignant tumor that originates in the nuclear layer of the retina. "We thus applied PNGase F treatment to fully deglycosylate the mature, membrane associated ATP1B2 in transfected HEK293 cells as well as in Y79 cells, an established human retinoblastoma cell line which endogenously expresses the retinal Na/K-ATPase." (PMID 31048931, 2019). "To investigate whether retinoschisin affects the potassium ion currents mediated by the Kv channels, we performed patch-clamp analyses using the retinal human retinoblastoma cell line Y-79, endogenously expressing Kv2.1, Kv8.2, ATP1A3, and ATP1B2, but not retinoschisin." (PMID 35876901, 2022).
Sepsis (2 papers, 2017 to 2025). Sepsis is defined as life-threatening organ dysfunction caused by a dysregulated host response to infection. "Integrating WGCNA with three machine learning algorithms, we identified six diagnostic genes—PGM3, GDF15, GART, GFOD2, E2F2, and ATP1B2—associated with sepsis-induced ALI, which were validated in clinical samples by Western blotting." (PMID 41142807, 2025).
acute respiratory distress syndrome (1 paper, 2025). Progressive and life-threatening pulmonary distress in the absence of an underlying pulmonary condition, usually following major trauma or surgery. "ATP1B2 encodes a regulatory subunit of the sodium/potassium-transporting ATPase pump, and its dysregulation may disrupt vascular endothelial and alveolar epithelial integrity, promoting capillary leak and acute respiratory distress syndrome." (PMID 41212055, 2025).
behavioural disorders (1 paper, 2015). "Finally, many genes associated with neurological development and behavioural disorders were pinpointed (CACNG2, CALN1, ACCN3, EFNB3, DLGAP1 and ATP1B2)." (PMID 26100250, 2015).
COVID-19 (1 paper, 2025). A disease caused by infection with severe acute respiratory syndrome coronavirus 2. "In a large, prospective, multicenter cohort, we find that either a single gene, OLAH, or a combination of 3 genes, CD83, ATP1B2, and DAAM2, accurately predicted 28-day mortality in hospitalized patients with COVID-19, including those who have been vaccinated." (PMID 41212055, 2025).
epithelial ovarian cancer (1 paper, 2007). "We evaluated whether common genetic variation in SHBG and its 3' neighbor ATP1B2, in linkage disequilibrium, is associated with the risk of epithelial ovarian cancer." (PMID 17411440, 2007). "This detailed evaluation of common genetic variation in SHBG including its neighboring gene ATP1B2, does not support a substantial association between common variants and ovarian cancer risk." (PMID 17411440, 2007).
Hypertension (1 paper, 2016). The presence of chronic increased pressure in the systemic arterial system. "Similarly, the pathway-based 2-locus epistasis analysis indicated significant interactions between INSR and PRKCG for SBP and MAP; INS and PIK3R2 for DBP; PIK3CD and ATP1B2 for hypertension in the real data set." (PMID 27980660, 2016).
laryngeal carcinoma (1 paper, 2025). Carcinoma that arises from the laryngeal epithelium. "For laryngeal cancer, rs55831773, a cross ancestral splice variant, mapping to ATP1B2 was associated with increased risk (OR (95% CI) = 1.21 (1.13, 1.29), pmeta = 5.1 × 10−9)." (PMID 41038832, 2025).
leukemia (1 paper, 2015). A malignant (clonal) hematologic disorder, involving hematopoietic stem cells and characterized by the presence of primitive or atypical myeloid or lymphoid cells in the bone marrow and the blood. "The role of ATP1B2 in the pathogenesis of leukemia has yet to be investigated." (PMID 26191006, 2015).
lymphoma (1 paper, 2020). A malignant (clonal) proliferation of B- lymphocytes or T- lymphocytes which involves the lymph nodes, bone marrow and/or extranodal sites.
pulmonary edema (1 paper, 2025). Accumulation of fluid in the lung tissues causing disturbance of the gas exchange that may lead to respiratory failure. "ATP1B2 encodes the β2 subunit of Na+/K+-ATPase, a crucial ion pump that maintains transmembrane electrochemical gradients, facilitates alveolar fluid clearance, and preserves epithelial barrier integrity; Na+/K+-ATPase dysfunction is a recognized mechanism of pulmonary edema in ALI." (PMID 41142807, 2025).
tumor (6 papers, 2017 to 2025). "DNA methylation analysis also revealed the methylation of multiple genes (FRMD6-AS2, SESN3, CYTL1, MIR4429, HIF3A, and ATP1B2) associated with tumor growth suppression." (PMID 36975488, 2023). "Furthermore, the methylation status of the ATP1B2 gene is associated with mechanisms of tumor growth inhibition." (PMID 41007990, 2025). "In addition, the methylation of FRMD6-AS2, SESN3, CYTL1, MIR4429, HIF3A, and ATP1B2, which are associated with tumor growth suppression, was also detected." (PMID 36975488, 2023). "Additionally, the methylation of FRMD6-AS2, SESN3, CYTL1, MIR4429, HIF3A, and ATP1B2, which are associated with tumor growth suppression, was detected by DNA methylation analysis." (PMID 36975488, 2023).
ATP1B2 also shares sentences with these, for which no sentence is quoted: schizophrenia (2 papers); asthma (1); bladder carcinoma (1); brain ischemia (1); breast tumors (1); cancer (1); cervical cancer (1); clear cell renal cell carcinoma (1); Dupuytren’s Disease (1); hepatocellular carcinoma (1); infection (1); malignant glioma (1); movement disorder (1); neurodegenerative disease (1); Neurological Diseases (1); ovarian cancer (1); polycystic kidney disease (1); sarcopenia (1).